CASP8 (caspase 8)
Diseases named in the same sentence as CASP8 in open-access papers (continued):
Sharing a sentence is not in itself a finding about the gene and the disease.
schizophrenia (3 papers, 2023 to 2026). A major psychotic disorder characterized by abnormalities in the perception or expression of reality. "Conversely, other TNFSF downstream mRNAs were unchanged (BAX, BID, CASP1, CASP3, CASP8, and CASP9) in high-inflammation schizophrenia cases compared with low-inflammation controls." (PMID 41567988, 2026).
tuberculosis (3 papers, 2012 to 2025). A chronic, recurrent infection caused by the bacterium Mycobacterium tuberculosis. "Interactions between dsRNA and TLR-8 result in caspase-8 activity and TLR-8 polymorphisms are associated with increased susceptibility to tuberculosis." (PMID 22253841, 2012). "Furthermore, CASP8, APOA1, CP and INFG were all enriched in tuberculosis." (PMID 40083347, 2025).
urogenital cancers (3 papers, 2021 to 2022). "Up-regulated CASP8 expressions were observed in other urogenital cancers including renal neoplasms." (PMID 35928267, 2022). "We further tested whether CASP8 is elevated in other genitourinary cancers including renal, bladder, and adrenal carcinoma." (PMID 33828176, 2021).
acute leukemia (2 papers, 2010 to 2025). A clonal (malignant) hematopoietic disorder with an acute onset, affecting the bone marrow and the peripheral blood. "Our current study seeks to extend these mechanistic studies to acute leukemia cells and to clarify the specific role of caspase-8 and the adaptor molecule Fas-associated death domain (FADD) in the mechanism of apoptosis induced by PCI-24781." (PMID 20145726, 2010). "The latest caspase-8 isoform was identified in patients with acute leukemia and is called caspase-8s." (PMID 39996713, 2025). "In the present study, we show that apoptosis induction and histone alterations by PCI-24781, a novel hydroxamic acid-based HDAC inhibitor, require caspase-8 and the adaptor molecule, Fas-associated death domain (FADD), in acute leukemia cells." (PMID 20145726, 2010).
adenoma (2 papers, 2021 to 2024). A neoplasm arising from the epithelium. "Five somatic mutations in the CASP8 gene were identified in 98 invasive colorectal carcinomas (5.1%) but not in any adenomas." (PMID 34836311, 2021). "Evaluating the similarities of significantly over-represented proteins in the adenoma and carcinoma cell lines, 226 proteins were identified, of which the most over-represented included proteins involved in signal transduction (NUCB1, ZYK) and apoptosis (RIPK3, CASP8)." (PMID 39462388, 2024).
alopecia (2 papers, 2021 to 2025). Hair loss usually from the scalp. "Screened common genes of Decursin and alopecia gene sets were CASP3, CASP7, CASP8, MAPK1, AKT1, and others." (PMID 34832932, 2021).
amyotrophic lateral sclerosis (2 papers, 2019 to 2025). Amyotrophic lateral sclerosis (ALS) is a neurodegenerative disease characterized by progressive muscular paralysis reflecting degeneration of motor neurons in the primary motor cortex, corticospinal tracts, brainstem and spinal cord. "It directly binds to and regulates the function of caspase-8, of proteasome-mediated RIPK1 stability in amyotrophic lateral sclerosis, as well as vesicle trafficking and autophagy, and therefore represents a promising regulator of vesicular ADAM15." (PMID 41340056, 2025). "Activated caspase 8 has been detected within insoluble elements in HD brains, and reported to be significantly up-regulated in cerebrospinal fluid in amyotrophic lateral sclerosis (ALS)." (PMID 31083628, 2019).
anal carcinoma (2 papers, 2016 to 2019). "In conclusion, we here demonstrate that low expression of Plk3 and low levels of pT273 caspase-8 detection may, especially if combined with HPV-16 DNA-load, provide valuable prognostic markers in anal cancer." (PMID 27462786, 2016). "Consequently, as the prevalence of HPV-DNA in anal carcinoma commonly exceeds 90%, our data on the interrelationship between HPV16 DNA load/p16INK4a immunostaining and Plk3 or pT273 caspase-8 expression may provide additional informations to a histopathological assessment." (PMID 27462786, 2016).
anemia (2 papers, 2024). A reduction in the number of red blood cells, the amount of hemoglobin, and/or the volume of packed red blood cells. "Casp8–/–Ripk3–/– double‐knockout mice exhibit higher levels of RBCs and platelets than Casp8–/–Mlkl–/– double‐knockout mice.[34a] Our study revealed that RIPK3 regulates Abin1Q478H/Q478H anemia through necroptosis‐independent mechanisms." (PMID 38009796, 2024).
autoinflammatory syndrome (2 papers, 2022 to 2025). A group of disorders of the innate immune system characterized by attacks of seemingly unprovoked inflammation without significant levels of either autoantibodies or autoreactive T cells more characteristic of autoimmune disease. "Consequently, mice and patients with mutations in the caspase-8 cleavage site of RIPK1 develop an autoinflammatory syndrome characterized by excessive RIPK1-dependent cell death." (PMID 40307618, 2025).
bone tumor (2 papers, 2021 to 2023). "We studied the Caspase-8 negative NB cell line SH-SY5Y14, which originally derived from a metastatic bone tumor biopsy and are a sub-line of the parental line SK-N-SH." (PMID 34011952, 2021).
cardiac hypertrophy (2 papers, 2012 to 2019). "Recently, initiator caspase-8 and activating caspase-3 have been reported to play a role in pathological cardiac hypertrophy, cardiac dilation and failure." (PMID 22936985, 2012). "In order to determine whether there is a causal relationship between senescence and cardiac hypertrophy, we used the INK‐ATTAC mouse model, in which a small molecule, AP20187 (AP), induces apoptosis through dimerisation of FKBP‐fused Casp8." (PMID 30737259, 2019).
cerebral malaria (2 papers, 2020 to 2022). A sequestration of Plasmodium falciparum in the brain, which can cause coma and/or seizures. "Caspase-8 was reported to be a primary mediator of systemic inflammatory response in P. chabaudi infected mice and in P. berghei experimental cerebral malaria." (PMID 35795683, 2022). "Here, we report that caspase-8 is a central mediator of systemic inflammation, septic shock in the Plasmodium chabaudi-infected mice and the P. berghei-induced experimental cerebral malaria (ECM)." (PMID 32929083, 2020).
Chagas disease (2 papers, 2021 to 2024). A parasitic infection caused by Trypanosoma cruzi. "The down-regulation of Casp8 reduced the apoptosis risk in cardiomyocytes elevated by the up-regulation of Fadd in Chagas disease following infection with Trypanosoma cruzi." (PMID 38534766, 2024). "For instance, with x = −1.178, the Chagas disease gene Casp8 (Caspase 8) would have been neglected, although it is significantly down-regulated because CUT = 1.159 < |x|." (PMID 38534766, 2024). "We identified the candidate genes and pathways related to Chagas disease for resisting T. cruzi, it is found that CASP2, CASP8, NOD1, MYD88, TLRs, IL-1s, NAIPs, etc, would be responsible for the T. cruzi infection." (PMID 34171992, 2021). "According to these known information, DEGs (CASP2, CASP8, NOD1, MYD88, TLRs, IL-1s, NAIPs) involved in Chagas disease here are screened, which have been proven to be correlated with the activation or inhibition of multiple Chagas disease related pathways." (PMID 34171992, 2021).
chondrosarcoma (2 papers, 2018 to 2022). A malignant cartilaginous matrix-producing mesenchymal neoplasm arising from the bone and soft tissue. "Our data revealed that the activity of caspase-8 and caspase-3 was significantly increased in a concentration-dependent fashion in chondrosarcoma cells, indicating the apoptosis was induced by shikonin derivatives in our cell system by the extrinsic pathway." (PMID 35820864, 2022).
chordoma (2 papers, 2014 to 2023). Chordomas are rare malignant tumors arising from embryonic remnants of the notochord in axial skeleton. "We were able to revert this status in U-CH1 cells by exposition to synthetic soluble Fasl, activating Caspase 8 in a time and dose dependent manner, showing that, in vitro chordoma cell line, the FAS/FASL pathway can be modulated." (PMID 25071022, 2014). "The obtained results indicate that FAS/FASL expression is dysregulated in chordoma and that the downstream Caspase 8 and 3 are mostly inactive in the SBCs analyzed." (PMID 25071022, 2014). "Genes central for module 2 (and thus probably important for functioning of chordomas in both clusters) were either responsible for cell division and DNA repair process (e.g. ATM, CHEK, BMI1, MDM2) or parts of inhibitors of apoptosis cascade (e.g. CASP2, CASP8, SIRT2)." (PMID 37434245, 2023).
chronic multifocal osteomyelitis (2 papers, 2019 to 2021). "Spleen tyrosine kinase (SYK) performs a key role upstream of caspase-1 and caspase-8, primarily upregulating NF-κB and IL-1β signaling in Pstpip2cmo mice, and induction of chronic multifocal osteomyelitis (CMO)." (PMID 33215255, 2021).
cognitive decline (2 papers, 2011 to 2024). "We do know that overexpression of caspase-1, caspase-2, caspase-3, caspase-6, and caspase-8 is linked to Aβ accumulation and cognitive decline in mouse models and patients with neurodegenerative diseases." (PMID 39625520, 2024). "Uninjured aged knockout mice showed improved learning and memory, implicating a possible role for caspase 8 in cognitive decline with aging." (PMID 21957448, 2011).
cognitive deficits (2 papers, 2023). "Notably, knockdown of TAK1, mediated by AAV-siTAK1, significantly increased RIPK1-caspase 8-mediated apoptosis and RIPK1-RIPK3-MLKL dependent necroptosis of neurons in the cerebral cortex and hippocampus, which was accompanied by the decrease of neurons and cognitive impairment." (PMID 37196118, 2023).
colorectal adenocarcinoma (2 papers, 2018 to 2023). The most common type of colorectal carcinoma. "The findings of this study indicate that the association of 5-FU and ASA leads to an increase in the expression of both caspases, caspase 3 and caspase 8, in colorectal adenocarcinoma cells." (PMID 37504320, 2023).
dementia (2 papers, 2019 to 2023). Loss of intellectual abilities interfering with an individual's social and occupational functions. "Our findings highlight the roles of several functionally pleiotropic proteins in AD, such as CASP8, which was increased in the plasma and CSF of AD-dementia patients, and in the plasma of Aβ+ MCI patients." (PMID 31694701, 2019).
dry eye (2 papers, 2015 to 2022). "We have also shown that in our inducible dry eye model neutralization of IFN-γ decreased caspase-3 and caspase-8 and increased conjunctival goblet density." (PMID 25889094, 2015).
dyslipidemia (2 papers, 2025). "In another example, dimerization-induced caspase-8 activation in adipocytes promotes metabolic syndrome during diet-induced and genetic obesity, and although this proves that acute cell death causes lipodystrophy, it does not shed light on the molecular events that control cell death in adipocytes." (PMID 40961178, 2025). "Noteworthy, although caspase-8 deficiency is sufficient to prevent lipodystrophy and metabolic syndrome in response to HFD, it does not fully prevent HFD-induced GWAT hypertrophy in HoipA-KO mice, possibly because of persistent caspase-3 activation, as noted by immunostaining." (PMID 40961178, 2025).
emphysema (2 papers, 2011). "Both caspases were elevated in lung explants with emphysema following 18 h of culture with rTRAIL compared to untreated lung tissues ([Area Under the Curve (AUC) rTRAIL treated/AUC untreated*100] Casp-3 +14.1%; Casp-8 +20.7%)." (PMID 21824395, 2011).
endothelial dysfunction (2 papers, 2022 to 2025). In vascular diseases, endothelial dysfunction is a systemic pathological state of the endothelium (the inner lining of blood vessels) and can be broadly defined as an imbalance between vasodilating and vasoconstricting substances produced by (or acting on) the endothelium. "These DORs were located at promoters of genes including CD74, IFI27, HLA-DMA, CASP8 and NOX4, which are associated with antigen presentation, inflammation and endothelial dysfunction." (PMID 41085167, 2025).
endotoxemia (2 papers, 2020 to 2024). "More recently, casp-8, that plays a central role in apoptosis, has been reported as an important mediator of endotoxemia resistance and LPS-driven systemic inflammation." (PMID 38372712, 2024). "Given the identified anti-inflammatory function of vICA, it will be worthwhile to assess whether vICA expression rescues the embryonic lethality or other CASP8-dependent inflammatory pathologies such as bacterial pneumonia and endotoxemia." (PMID 33126536, 2020).
epithelial dysplasia (2 papers, 2009 to 2022). "In addition, methylation of KLLN, CHFR, TP73, GSTP1, and CASP8 may be related to precancerous processes, such as epithelial hyperplasia and epithelial dysplasia." (PMID 35681626, 2022). "We presume that in intraepithelial neoplasia, the body compensatorily up-regulates the expression of IGFBP-5, which activates the caspase-8 signal transduction pathway, increases the structure sensitivity to TNF-α, induces the internal apoptosis pathway, and delays tumor advancement." (PMID 19476635, 2009).
glomerulonephritis (2 papers, 2022 to 2024). A renal disorder characterized by damage in the glomeruli. "This study reveals that the activation of caspase-8 in neutrophils can worsen glomerulonephritis of AAVs by regulating inflammation and immunity." (PMID 36505410, 2022).
gout (2 papers, 2020 to 2022). A condition characterized by painful swelling of the joints, which is caused by deposition of urate crystals. "PTGS2, CASP8, NFE2L2, and CD274 were identified as key pyroptosis-related genes associated with gout." (PMID 36291136, 2022). "miR-16-5p, miR-128-3p, miR-20a-5p, and miR-155-5p can potentially influence pyroptosis and the occurrence and development of gout by affecting the expression of the PTGS2, CASP8, NFE2L2, and CD274 genes." (PMID 36291136, 2022). "Experimental validation revealed that PTGS2 and NFE2L2 were significantly upregulated, and CASP8 and CD274 were significantly downregulated in gout." (PMID 36291136, 2022). "The therapeutic targets through which Simiao decoction alleviated gouty arthritis were p-STAT3, APOB, CASP8, c-FOS, PPARα, FN1, and LPL." (PMID 32670069, 2020).
Hepatitis B (2 papers, 2020 to 2021). "The key target genes enriched in the Hepatitis B pathway include MAP2K1 and CASP8." (PMID 33863948, 2021).
Herpes simplex infection (2 papers, 2022). "The KEGG pathway analysis highlighted that a large number of genes that were up-regulated after infection with V2 were the same as those upregulated in response to Herpes simplex infection (genes Myd88, Irf7, H2-Q7, Casp8, Tlr3, Daxx, C3, H2-Aa, Oas2, Oas3, H2-T22, H2-T23 and Cd74)." (PMID 35458422, 2022).
Hypoglycemia (2 papers, 2021 to 2023). A decreased concentration of glucose in the blood. "BID inhibition also prevented nuclear translocation of the pro-apoptotic factor AIF in models of hypoxia–hypoglycemia-induced neuronal cell death, although the role of caspase 8 in AIF release from mitochondria was not elucidated in this study, and a role for PARP activation was proposed." (PMID 34708044, 2021).
infertile (2 papers, 2020 to 2025). "MR results revealed genetic correlations between abnormal ADA, artemin, OSM, caspase 8, CXCL5, interleukin‐18, and LIFR levels and infertility." (PMID 40525280, 2025).
Legionella infection (2 papers, 2023 to 2025). "Furthermore, caspase-8 is required for control of pulmonary Legionella infection." (PMID 37279255, 2023).
leukocytosis (2 papers, 2014 to 2021). "Caspase-8 heterozygosity or Bid deletion did not prevent the leukocytosis, whereas Ripk3 and Mlkl deletion markedly reduced it, suggesting the hematopoietic phenotype is driven predominantly by necroptosis." (PMID 25443632, 2014).
lipodystrophy (2 papers, 2021 to 2025). A congenital or acquired disorder characterized by abnormal loss or redistribution of the adipose tissue in the body. "Inhibiting caspase-8–mediated cell death is sufficient to prevent lipodystrophy and MASLD in HoipA-KO obese mice." (PMID 40961178, 2025). "In turn, the prevention of caspase-8–dependent cell death prevents lipodystrophy caused by the absence of HOIP." (PMID 40961178, 2025).
liver disease (2 papers, 2023 to 2024). "Apoptosis and programed necrosis/necroptosis are the major types of cell death in liver disease, with Caspase-8 representing a central switch that directs cell death towards apoptosis or necroptosis." (PMID 37563155, 2023).
malignant glioma (2 papers, 2018 to 2022). A grade III or grade IV glioma arising from the central nervous system. "Caspase-8 expression levels were found to be lower in normal brain tissue than those in malignant glioma, while patients with overexpression of caspase-8 were in the earlier stages." (PMID 35846123, 2022). "At the cellular level, caspase-8 can inhibit malignant glioma cell proliferation." (PMID 35846123, 2022).
mastitis (2 papers, 2024 to 2025). Inflammation of breast tissue during lactation or postpartum due to an obstructed duct or infection. "Concurrently, elevated expression of the apoptosis-related genes caspase-8 (cas8) and APOE activates apoptotic pathways, while the activation of metabolic pathways collectively drives the onset and progression of mastitis." (PMID 41305370, 2025).
microphthalmia (2 papers, 2019 to 2024). Congenital or developmental anomaly in which the eyeballs are abnormally small. "Our data combined with previous studies of microphthalmia may suggest apoptosis modulated through CASP8 and the TNF death receptor is a shared pathway contributing to ocular malformation, as alternative cell death pathways are likely involved in developmental eye disorders." (PMID 38821055, 2024). "Moreover, immunoblot analysis of caspase 8 and 9 revealed no activation in retinas deleted for YME1L, indicating that the loss of YME1L induces microphthalmia along a different pathway." (PMID 30389680, 2019).
Myelodysplasia (2 papers, 2018 to 2024). Clonal hematopoietic stem cell disorders characterized by dysplasia (ineffective production) in one or more hematopoietic cell lineages, leading to anemia and cytopenia. "The phenotype of our Casp8−/− mice resembles most of the clinical characteristics of MDS patients, including cytopenia and myelodysplasia at 4 months after induction of Casp8 deletion." (PMID 38637559, 2024).
myocardial ischemia (2 papers, 2020 to 2021). A disorder of cardiac function caused by insufficient blood flow to the muscle tissue of the heart. "TNF-α-induced caspase-8 activation results in the leakage of RyR2 channels that promote cardiac remodeling after myocardial ischemia/reperfusion." (PMID 33796569, 2021). "Tumor necrosis factor-α (TNF-α), caspase-8, and complement component 5a receptor (C5aR) are known to play a crucial role in the myocardial ischemia/reperfusion (I/R) injury in cardiac transplantation." (PMID 32686827, 2020).
neuroendocrine lung tumors (2 papers, 2010 to 2023). "Methylation of CASP8 gene has also been reported in some childhood tumors and in neuroendocrine lung tumors." (PMID 20132554, 2010).